FOXO1 (forkhead box O1)
Diseases named in the same sentence as FOXO1 in open-access papers (continued):
Sharing a sentence is not in itself a finding about the gene and the disease.
prostate carcinoma (continued). "Transfection of miR-370 consistently and dose-dependently reduced the luciferase activity of the FOXO1 3′-UTR luciferase reporter plasmid in PC3 and DU145 prostate cancer cells." (PMID 23029264, 2012). "Furthermore, FOXO1, LATS2, and RB1 have been shown to act as tumor suppressor genes in various prostate cancer models." (PMID 38658552, 2024). "Moreover, using DU145 prostate cancer cells, it was previously demonstrated that SIRT1 deacetylates and deactivates FOXO1 transcription activities." (PMID 36291902, 2022). "Similarly, in PTEN-negative prostate cancer, PI3K/AKT signaling is activated and the downregulation of FOXO1 contributes to the hyperactivation of AR, thereby driving the castration-resistant progression of PC." (PMID 33921222, 2021). "ChIP-qPCR analysis further confirmed that there was substantial enrichment of EZH2 binding at the FOXO1 promoter in both C4-2 (PTEN-negative) and 22Rv1 (PTEN-positive) prostate cancer cells, indicating that EZH2 binds to the FOXO1 gene promoter in both cell lines." (PMID 31410199, 2019). "According to these researchers, overexpression of miR-96 decreases FOXO1 expression in both the non-malignant tissue samples and the prostate cancer tissue samples, even when the two samples are combined." (PMID 33869675, 2019). "The identification of FOXO1 and ATG5/GLUT1 in purified stroma and their differential expression in aggressive vs. indolent prostate cancer samples indicate that it is possible to clinically categorize PCa in terms of the metabolic responses, namely RWE, that it elicits in the stroma." (PMID 27152194, 2016). "During the development of human prostate cancer, chromosome 13q is one of the most frequently deleted chromosomes, and the deletion involves multiple regions and genetic foci in 13q14 and 13q21, including RB1 and FOXO1 at 13q14 and KLF5 at 13q21." (PMID 25896712, 2015). "FOXO1 also inhibits RUNX2-mediated migration and invasion of prostate cancer cells." (PMID 26204939, 2015). "miR-370 overexpression increased prostate cancer cell growth, and this effect of miR-370 on cell proliferation was decreased in the absence of FOXO1 3′UTR." (PMID 25628647, 2014). "In particular, after transfection of a FOXO1 reporter gene and miR-370 into PC3 and DU145 prostate cancer cells, luciferase activity could be restored by overexpression of FOXO1 and partially rescued by transfection of the FOXO1-3′-UTR." (PMID 23029264, 2012). "Indeed, treatment of prostate cancer cells with the CDK inhibitor roscovitine and the PI3K inhibitor LY294002 synergistically induces expression of the FOXO1 target gene BIM." (PMID 23029264, 2012). "However, SIRT1 expression is increased in human prostate cancer tissues, compared with adjacent normal prostate tissues, and SIRT1 promotes prostate cancer by deacetylating and inactivating FOXO1 protein and by protecting cells against oxidative stress." (PMID 21698133, 2011). "We then researched FOXO1's function concerning cell proliferation in PC-3 and LNCaP cells by using the CCK-8 assay and found that knockdown of FOXO1 could significantly inhibit prostate cancer cell proliferation." (PMID 34552661, 2021). "FOXO1 has also been shown to bind and inhibit the transcriptional activity of E26 transformation-specific (ETS) transcription factor ERG, which is over-expressed in 50% of prostate cancers owing to TMPRSS2-ERG (transmembrane protease, serine 2: ERG fusion) gene rearrangements." (PMID 32630372, 2020). "However there was no report about FOXO1 regulated by microRNA in prostate cancer to promote proliferation clearly and directly yet." (PMID 23029264, 2012). "Thus, it is conceivable that EZH2 inhibitor can reverse EZH2-mediated repression of FOXO1 expression in both PTEN positive and negative prostate cancer cells; however, it induces substantial death only in PTEN-positive cells where FOXO1 protein is primarily located in the nucleus." (PMID 31410199, 2019).
hepatocellular carcinoma (89 papers, 2012 to 2026). A malignant tumor that arises from hepatocytes. "HDAC9-mediated deacetylation of FOXO1 has been linked to increased FOXO1 activity in human hepatoma cells." (PMID 41416997, 2025). "The rs17592236 SNP is a target site of the human miRNA miR-137, and the rs17592236 polymorphism is associated with a lower hepatocellular carcinoma hereditary susceptibility likely through modulating the binding affinity of miR-137 to the 3’UTR in FOXO1 messenger RNA." (PMID 31492105, 2019). "Studies have shown that it can inhibit the migration and invasion of hepatocellular carcinoma cells and regulate metastasis-related pathways such as FOXO1 and VEGF." (PMID 41373733, 2025). "Studies in hepatoma cells suggest that FoxO1 controls the transcription of reporter genes containing the PCK promoters." (PMID 36448290, 2023). "For instance, the overexpression (OE) of miR-3174 significantly promotes cell proliferation and inhibits cell apoptosis by suppressing forkhead box protein O1 (FOXO1) expression in hepatocellular carcinoma." (PMID 36629518, 2023). "According to a recent study, FOXO1 silencing can decrease epithelial-mesenchymal transitions (EMT) in hepatocellular carcinoma." (PMID 36555288, 2022). "HDAC9 promotes the nuclear accumulation of FOXO1 and increases FOXO1 activity by deacetylation of FOXO1 protein in hepatocellular carcinoma." (PMID 35203583, 2022). "FOXO1 silencing by siRNA in hepatocellular carcinoma reduced epithelial and enhanced mesenchymal marker expression indicating EMT." (PMID 35164673, 2022). "It is noteworthy that the invasion, EMT and metastasis of hepatocellular carcinoma can be decreased by FOXO1 via ZEB2." (PMID 34511023, 2021). "Meanwhile, a similar group of microRNAs, miR-193, miR-96 and miR-182, also suppress FOXO1 expression in hepatocellular carcinoma, resulting in enhanced cell invasion and metastasis." (PMID 32372224, 2020). "Significantly, we found that HDIs induced autophagy through the FOXO1-dependent pathway, and inhibition of FOXO1 sensitized hepatoma cells to HDIs and overcame autophagy-mediated metastasis." (PMID 32929346, 2020). "A recent study shows that FOXO1 silencing using small interfering ribonucleic acid (siRNA) in hepatocellular carcinoma enhances mesenchymal and reduces epithelial marker expression, as in EMT." (PMID 32372224, 2020). "Unexpectedly, we identified a pro-metastasis function of FOXO1 in hepatoma cells by activating autophagy." (PMID 32929346, 2020). "Specifically, FOXO1 expression is inversely correlated with the expression of epithelial–mesenchymal transition (EMT) markers for metastasis in hepatocellular cancer (HCC)." (PMID 32629884, 2020). "Contrary to liver steatosis, a recent work using subcutaneously xenografted liver tumors in nude mice showed that hepatic AQP9 overexpression inhibit hepatocellular carcinoma by upregulating forkhead-box protein O1 (FOXO1) expression." (PMID 30042691, 2018). "Both CAR and PXR were demonstrated to interact with FOXO1 in HepG2 human hepatoma cells, and FOXO1 was then identified as a coactivator of CAR and PXR in these cells." (PMID 28818793, 2017). "Based on these collective findings, we propose that T3/TR inhibits the apoptotic effects of chemotherapeutic drugs in hepatoma cells through suppressing expression of the apoptosis regulator FoxO1 and its downstream target Bim." (PMID 27490929, 2016). "Another study demonstrated that in HCT116 colorectal cancer cells, HeLacervical cancer cells and HuH-7 hepatoma cells, miR-223 regulated FOXO1 expressionand cell proliferation." (PMID 24303815, 2014). "miR-96 has also been shown to target FOXO1 in endometrial, breast, hepatocellular cancer cells and Hodgkin lymphoma." (PMID 23951320, 2013).
hepatocellular carcinoma (continued). "In endometrial, breast and hepatocellular cancer, miR-96 has been shown to target the tumor suppressor FOXO1." (PMID 23951320, 2013). "miR-96 has been shown to decrease the mRNA level of FOXO1 significantly in hepatocellular carcinoma cells and decrease the protein levels slightly." (PMID 23951320, 2013). "In current study, the mechanism of MKP-3/FOXO1 interaction and the effects on transcription of gluconeogenic gene and glucose output was investigated in Fao hepatoma cells by using mutated MKP-3 and FOXO1 adenoviral constructs." (PMID 22848439, 2012). "In this study, the mechanism of MKP-3/FOXO1 interaction and the effect on transcription of gluconeogenic genes and glucose output has been investigated in Fao hepatoma cells." (PMID 22848439, 2012). "Moreover, in an earlier investigation on hepatocellular cancer, forkhead box O1 (FOXO1) was determined as an additional target gene for the LINC01018/hsa-miR-182-5p axis." (PMID 37675122, 2023). "A previous study showed that silencing FOXO1 in hepatocellular carcinoma can enhance EMT." (PMID 36555288, 2022). "Hsa-circ-0110102, as a cancer-causing circRNA, inhibits the expression of CCL2 in HCC cells through the sponge effect of miR-580-5p, CCL2 further activates the COX-2/PGE2 pathway in macrophages in a FOXO1-dependent manner, and promotes the progress of hepatocellular carcinoma." (PMID 35806027, 2022). "Enriched pathway, in which the FOXO transcription factor family plays an important role in tumor proliferation and apoptosis, FOXO1 was shown to play a repressive role in hepatocellular carcinoma, and other FOXO transcription factors have been shown to be associated with hepatocellular carcinoma." (PMID 36479313, 2022). "However, there were still conflicting reports that miR-3127 actually acted as an oncogene in hepatocellular carcinoma by activating AKT/FOXO1 signaling, via directly targeting the 3′-UTR of PHLPP1/2." (PMID 32194636, 2020). "However, miR-3127 promotes the proliferation and tumorigenesis in hepatocellular carcinoma by inducing the AKT/FOXO1 signaling." (PMID 32194636, 2020). "In particular, we observed an enrichment of miR-192-5p target genes involved in telomere maintenance and hepatocellular carcinoma and in the signaling pathway of FOXO1, a transcription factor that plays important roles in the regulation of gluconeogenesis and glycogenolysis by insulin signaling." (PMID 32620541, 2020). "Moreover, our results suggested that the autophagy induction by FOXO1 was responsible for HDI-induced hepatoma cell metastasis since FOXO1 knockdown in hepatoma cells blocked HDIs-induced HCC cell autophagy, EMT, invasion, and migration." (PMID 32929346, 2020). "The present study found that HDIs could induce autophagy in hepatoma cells by upregulating FOXO1 and ULK1." (PMID 32929346, 2020). "In conclusion, our results suggest that HDIs trigger FOXO1-dependent autophagy in hepatoma cells that may ultimately limit the clinical outcomes of HDI-based therapies." (PMID 32929346, 2020). "Therefore, we first investigated FOXO1 expression in HDI-treated hepatoma cells by gene expression profiling." (PMID 32929346, 2020). "Furthermore, HDIs induced autophagy through a Forkhead box O1(FOXO1)-dependent pathway, and inhibition of FOXO1 sensitized hepatoma cells to HDIs and overcame autophagy-mediated metastasis." (PMID 32929346, 2020). "It was reported that miR-96 targeted the 3ʹ-UTR of SOX6, FOXO1 and FOXO3a in hepatoma cells." (PMID 33046975, 2020). "Furthermore, Wu and colleagues have reported FoxO1 as the putative target of miR‐223 in colorectal cancer cells, cervical cancer cells and hepatoma cells." (PMID 29083107, 2018).
hepatocellular carcinoma (continued). "Notably, T3 effect on the repression of FoxO1 and Bim proteins was observed in Huh7, a hepatoma cell line expressing endogenous TR proteins." (PMID 27490929, 2016). "Thus, our findings provide novel insights into the molecular mechanisms underlying HDI-induced metastasis involving FOXO1-mediated autophagy and suggest that combining an HDI and a FOXO1 inhibitor is a more effective therapeutic paradigm for the treatment of hepatocellular carcinoma." (PMID 32929346, 2020). "The same miRNA is up-regulated in hepatocellular carcinoma (HCC) patients and was found to promote migration and invasion through targeting of FOXO1." (PMID 31906022, 2019). "FOXO1 silencing by siRNA in hepatocellular carcinoma (HCC) cell lines enhanced the expression of mesenchymal markers and decreased the expression of the epithelial markers." (PMID 27924058, 2017). "When AQP9 was overexpressed in SMMC7721 human hepatoma cell line, cell colony formation was reduced due to cell cycle arrest at G1 phase and increased apoptosis, which was linked to reduced PI3K and P-Akt levels and increased forkhead box protein O1 (FOXO1) levels." (PMID 27329843, 2016). "miR-96 promotes hepatocellular carcinoma (HCC) cell proliferation and colony formation by targeting FOXO1 and FOXO3a." (PMID 24335145, 2014). "In hepatocellular carcinoma (HCC), FOXO1 has been shown to be downregulated in liver tissues, and the lower expression has been correlated with poor prognosis." (PMID 41777650, 2026). "It has been reported to reduce the mRNA and protein levels of MDR1 in human hepatocellular carcinoma cell line HepG2 by down-regulating the human ABCA1 gene involved in multiple transcription factors, such as FOXO1." (PMID 40284452, 2025). "Additionally, the FOXM1/RB1/DNMT3B transcriptional regulatory complex can suppress the expression of FOXO1, resulting in decreased levels of FOXO1 target p16, p21, and p27 in hepatocellular carcinoma (HCC)." (PMID 38672640, 2024). "Previous studies have also found that miR-183-5p promotes hepatocellular carcinoma progression via regulate IRS1 expression and promotes the invasion and proliferation thyroid cancer cells by regulating FOXO1." (PMID 37548821, 2023). "In fact, mouse hepatoma cells (Hepa1–6) treated with 2.5 μM dexamethasone for 2 h, displayed increased expression of MKP3 via the forkhead box protein O1 (FOXO1) and the same result was obtained in lean mice treated with 15 mg/kg dexamethasone for 28 days." (PMID 35052872, 2022). "For hepatocellular carcinoma, AQP9 suppresses hepatocellular carcinoma cell growth and metastasis via distinct pathways, including HIF-1α, PI3k/Akt, Wnt/β-catenin, and FOXO1." (PMID 35972604, 2022). "Foxo1 is the main FOXO protein that promotes the occurrence and development of hepatocellular carcinoma." (PMID 36374212, 2022). "To further explore the function of miR-9-5p/FOXO1/CPEB3 FFL in vivo, we built hepatoma xenografts in nude mice." (PMID 35805200, 2022). "Meanwhile, HDAC6 binds to cytoplasmic Foxo1 at K242 and deacetylates Foxo1 to weak the stability of Foxo1 and inhibit nucleus translocation, which limits IL-17–producing helper T (TH17) pathogenicity and antitumor effect in hepatocellular carcinoma." (PMID 34880761, 2021). "The results demonstrated that HDIs upregulated FOXO1 and ULK1 in hepatoma cells in a time-dependent manner, indicating their key regulatory role in HDI-induced autophagy." (PMID 32929346, 2020). "Using RNA sequencing analysis, we found that FOXO1 and ULK1, two autophagy-related genes, were significantly upregulated in HDI-treated HCC cells, whereas the knockdown of FOXO1 or ULK1 blocked HDI-induced autophagy and EMT in hepatoma cells." (PMID 32929346, 2020). "Polydatin, a natural precursor of resveratrol, also upregulates FOXO1 through inhibition of Akt and STAT3 signalling pathway to suppress hepatocellular carcinoma cell migration and invasion." (PMID 32372224, 2020).
hepatocellular carcinoma (continued). "HDIs induced autophagy via a FOXO1-dependent pathway, and FOXO1 inhibition promoted HDI-mediated apoptosis in hepatoma cells." (PMID 32929346, 2020). "In liver carcinoma cells, PPAR can also interfere with the binding of apolipoprotein C III (ApoC-III) to FOXO1, affecting the lipid metabolism and serum triglyceride levels." (PMID 32372224, 2020). "On the other hand, miR-411-5p as an oncogene targeted FOXO1 and ITCH to promote cell cycle process and proliferation in NSCLC and hepatocellular carcinoma." (PMID 30390072, 2019). "In hepatocellular carcinoma (HCC) cells, suppression of FOXO1 by miR-1269 was related to dysregulation of cyclin D1 and Ki67 expression, suggesting a critical role in the growth of HCC cells." (PMID 30360388, 2018). "On the contrary, our data shows direct interactions among FOXO1, HDAC3, and HDAC4 in HepG2 which is a well-differentiated hepatocellular carcinoma of humans." (PMID 30424007, 2018). "In HepG2 human hepatoma cells, zinc activates the PI3K/Akt pathway, inducing the phosphorylation, inactivation and nuclear exclusion of FoxO1." (PMID 22427991, 2012). "Furthermore, FOXO‐1 mRNA is a validated target of miR‐196a in cervical cancer, hepatocellular carcinoma, and lung cancer, and inhibits EMT in hepatocellular carcinoma." (PMID 40955778, 2025). "However, SIRT1 enhances transcription of the gluconeogenic genes, G6pc and Pck1, by deacetylating peroxisome proliferator-activated receptor γ coactivator-1α (PGC-1α) and Forkhead box O1 (FOXO1) in Sv40 hepatocytes and H4IIE rat hepatoma cells." (PMID 39372420, 2024). "The upregulation of FOXO1 and/or FOXO3 in cells undergoing apoptosis after blockade of the PI3K pathway suggested the involvement of FOXO1/3 in the induction of PUMA and BIM, as previously reported in cell lines derived from hepatocellular carcinoma and colorectal cancers." (PMID 36849535, 2023). "It was previously reported that PI3K inhibition induces apoptosis by upregulating forkhead box O1/3 (FOXO1/3), transcription factors downstream of PI3K signaling, and thereby transactivate the expression of PUMA or BIM in hepatocellular carcinoma and colorectal cancer, respectively." (PMID 36849535, 2023). "Thus, we alternatively stimulated HepG2 cells (human hepatoma cell line) with Pg-derived LPS or human recombinant IL-1β as positive control and examined mRNA expressions of CCL2, CXCL10, and FOXO1 using real time PCR." (PMID 34526589, 2021). "We investigated the effect of the long noncoding RNA (lncRNA) maternally expressed gene 3 (MEG3) on hepatocellular carcinoma (HCC) tumorigenesis and progression by targeting miR-5195-3p and transcription factor forkhead box O1 (FOXO1) to identify a novel target for HCC treatment." (PMID 34895065, 2021). "In hepatocellular carcinoma, TFP could activate forkhead box O1 (FOXO1)–related signals to inhibit tumor growth." (PMID 31572198, 2019). "While the role of FOXO1 in the HDACIs-induced autophagy has not been directly demonstrated and characterized, HDACIs induce protective autophagy by sustaining the expression and transcriptional activity of FOXO1 in HCT116 colon cancer cells and HepG2 hepatoma cells." (PMID 31546746, 2019). "In addition, phosphorylation of protein kinase B (Akt) by binding at Ser473 activates the transcription factor forkhead box protein O1 (FOXO1), which, in turn, inhibits the expression of both PEPCK and G6Pase in high-fat diet (HFD)-fed mice and in hepatocellular carcinoma (HepG2) cells." (PMID 33669133, 2021).